SIK2 (salt inducible kinase 2)
Description:
Serine/threonine-protein kinase that plays a role in many biological processes such as fatty acid oxidation, autophagy, immune response or glucose metabolism. Phosphorylates 'Ser-794' of IRS1 in insulin-stimulated adipocytes, potentially modulating the efficiency of insulin signal transduction. Inhibits CREB activity by phosphorylating and repressing TORCs, the CREB-specific coactivators. Phosphorylates EP300 and thus inhibits its histone acetyltransferase activity. In turn, regulates the DNA-binding ability of several transcription factors such as PPARA or MLXIPL. Also plays a role in thymic T-cell development (By similarity).
Synonyms: SIK-2; KIAA0781; QIK; SNF1LK2; DKFZp434K1115; LOH11CR1I
Tractability: Small molecule: a high-quality ligand is known; it belongs to a druggable protein family. PROTAC: it is named in the literature on targeted protein degradation; ubiquitination databases record sites on it; its protein half-life has been measured; a small molecule that binds it is known.
Target class: CAMK protein kinase group; CAMK protein kinase CAMK1 family; Protein Kinase; Kinase; Enzyme; CAMK protein kinase QIK subfamily
Chemical probes: GPLG3970 (high quality), HG-9-91-01 (high quality), JRD-SIK1/2i-4 (high quality), MRIA9 (high quality), YKL-05-099 (high quality), YKL-05-099, YKL-06-061 (high quality)
Gene: Protein-coding gene on chromosome 11 (111,602,404 to 111,730,855, forward strand). Ensembl gene ENSG00000170145.
Subcellular location: Cytoplasm; Endoplasmic reticulum membrane
Subcellular location (Human Protein Atlas): Nucleoplasm; Vesicles; Cytosol; Intermediate filaments; Nuclear speckles
Gene Ontology:
Molecular function: ATP binding; magnesium ion binding; protein binding; protein serine kinase activity; protein serine/threonine kinase activity; protein kinase activity
Biological process: intracellular signal transduction; positive regulation of ERAD pathway; protein autophosphorylation; protein phosphorylation; regulation of insulin receptor signaling pathway
Cellular component: endoplasmic reticulum membrane; cytoplasm; nucleus
Genetic constraint (gnomAD): Loss-of-function variants: 29 observed, 95.41 expected, observed/expected ratio (o/e) 0.3, 90% interval 0.22 to 0.41. The upper end of that interval is the gene's LOEUF score, 0.41, which puts it in group 1 of 6, group 1 being the genes least tolerant of losing a copy. Missense variants: 850 observed, 1,146.5 expected, observed/expected ratio (o/e) 0.74, 90% interval 0.7 to 0.79. Synonymous variants: 402 observed, 445.1 expected, observed/expected ratio (o/e) 0.9, 90% interval 0.83 to 0.98.
Homologues: Orthologues: chimpanzee SIK2 (99% identical), macaque SIK2 (98% identical), rabbit SIK2 (92% identical), mouse Sik2 (91% identical), rat Sik2 (89% identical), pig SIK2 (87% identical), guinea pig SIK2 (86% identical), tropical clawed frog sik2 (72% identical), zebrafish sik2b (66% identical), zebrafish sik2a (57% identical), Drosophila melanogaster Sik2 (40% identical), Caenorhabditis elegans kin-29 (26% identical). Paralogues in human: SIK1 (41% identical), SIK3 (37% identical), BRSK1 (22% identical), BRSK2 (22% identical), PRKAA2 (20% identical), SNRK (20% identical), NUAK1 (19% identical), NUAK2 (19% identical), PRKAA1 (19% identical), HUNK (18% identical), MELK (17% identical), NIM1K (15% identical), and 5 more.
Diseases named in the same sentence as SIK2 in open-access papers:
SIK2 is named in the same sentence as 76 diseases in open-access papers, as found by Europe PMC text mining. Sharing a sentence is not in itself a finding about the gene and the disease. The quoted sentences say what the papers report.
ovarian carcinoma (50 papers, 2011 to 2025). A malignant neoplasm originating from the surface ovarian epithelium. "Studies have demonstrated that SIK2 regulates cellular mitosis and that its targeted inhibition can make ovarian cancer cells more susceptible to the chemotherapy drug paclitaxel." (PMID 40612876, 2025). "SIK2 is emerging as an interesting target in ovarian cancer, and the underlying pathways have been investigated as follows." (PMID 36731029, 2023). "As a result, inhibition of SIK2 causes spindle assembly and centrosome function failure, which leads to improper spindle orientation and genomic instability for ovarian cancer cells." (PMID 36731029, 2023). "SIK2 was shown to be upregulated in adipose tissue-associated ovarian cancer cells and demonstrated to promote ovarian cancer cell fatty acid oxidation." (PMID 35565396, 2022). "Similarly, inhibition of SIK2 in a second ovarian cancer cell line, A2780, also caused a dose-dependent and significant reduction in the mitotic indices compared to DMSO treated cells (DMSO, 34.2%; 1 μM MRIA9, 25.2%; 5 μM MRIA9, 18.5%)." (PMID 34359562, 2021). "Furthermore, SIK2 overexpression has been described in almost 30% of ovarian cancer patients and was associated with a poor prognosis." (PMID 34359562, 2021). "Likewise, SIK3 has been documented as a putative tumour-associated antigen with expression in 55% of ovarian cancer samples, and, like SIK2, can control cell cycle progression at the G1/S checkpoint." (PMID 26068970, 2015). "Our previous studies revealed that SIC-19 targets SIK2 to induce DNA damage in ovarian cancer cells, so we next investigated the involvement of SIC-19 in triple-negative breast cancer and pancreatic cancer." (PMID 40612876, 2025). "Our previous research also demonstrated that SIC-19, which targets SIK2, affects DNA HR repair and increases the vulnerability of ovarian cancer cells to PARP inhibitors by inhibiting phosphorylation at RAD50-Ser635." (PMID 40612876, 2025). "SIK2 phosphorylates a range of substrates contributing to ovarian cancer cell motility, migration, metastasis, and the maintenance of breast cancer stemness." (PMID 39877288, 2025). "Research indicates that the knockdown of SIK2 in colorectal and ovarian cancer cells results in a 50% reduction in cellular glucose metabolism, underscoring SIK2’s significant regulatory influence on this metabolic pathway." (PMID 40868174, 2025). "By directly phosphorylating RAD50 at the Ser635 site in ovarian cancer, SIK2 can influence nuclear microfilament formation and DNA recombination repair, which in turn affects sensitivity to PARP inhibitors." (PMID 40612876, 2025). "Transgenic overexpression of SIK2 in ovarian cancer cells promotes abdominal metastasis, while SIK2 depletion prevents metastasis in vivo." (PMID 40384110, 2025). "Another study reported that SIK2 positively regulates the FAO gene program in ovarian cancer metastasis." (PMID 40384110, 2025). "Salt-inducible kinase 2 (SIK2), an AMPK-related protein kinase that has a positive effect on ovarian cancer progression, phosphorylates HDACs IIa, causing its cytoplasmic localization and inhibiting its binding to MEF2." (PMID 39624079, 2024). "SIK2 has a role in tumorigenesis in prostate and ovarian cancers, and SIK2 and SIK3 promote the growth of acute myeloid leukemia (AML) by inhibiting HDAC4 function." (PMID 39139449, 2024). "Salt inducible kinase 2 (SIK2) phosphorylates DRP1 S616 in ovarian cancer cells and therefore promotes mitochondrial fission, supporting tumour cell survival." (PMID 38434478, 2024). "It has been reported that SIK2 increased lipid contents through upregulating the expressions of lipogenic enzymes, resulting in tumor growth in ovarian cancer." (PMID 38914663, 2024). "Because miRNA3652 is downregulated in ovarian cancer cells, NFIB and SIK2 are increased, which causes ovary cells to produce reactive metabolites, mutagenic DNA adducts, and free radicals." (PMID 37845675, 2023).
ovarian carcinoma (continued). "In support, SIK2 knockout increases the sensitivity of ovarian cancer cells to paclitaxel and SIK2 expression is higher in paclitaxel-resistant cancer cells." (PMID 36731029, 2023). "As a result, there is extensive literature on the discovery of novel and specific inhibitors of SIK2 as a primary treatment or secondary treatment to enhance chemotherapeutic efficacy for ovarian cancer." (PMID 36731029, 2023). "SIK2 overexpression in human ovarian cancer cells increases F-actin expression and MYL2 phosphorylation, which significantly promotes ovarian cancer metastasis." (PMID 36731029, 2023). "SIK2 promotes the growth of ovarian cancer cells by increasing cell proliferation and EMT while inhibiting apoptosis." (PMID 37508561, 2023). "Metabolic programming in ovarian cancer cells is influenced by salt-inducible kinase 2 (SIK2), a member of the AMPK family." (PMID 37508561, 2023). "Meanwhile, upregulation of miR-149-5p blocked PTX resistance via targeting SIK2 in PTX-resistant ovarian cancer cells." (PMID 38152652, 2023). "Ovarian cancer is highly metastatic and often presents in the omentum, an adipocyte-rich tissue in the abdominal cavity, and the overexpression of SIK2 is observed in ovarian cancer metastasis." (PMID 36731029, 2023). "SIK2 induces the Warburg effect in ovarian cancer cells by upregulating HIF-1a expression, through activation of the PI3K/AKT signaling pathway." (PMID 37508561, 2023). "Consistently, depletion of SIK2 in mouse xenografts sensitized ovarian cancers to tubulin-targeting drug paclitaxel, identifying SIK2 as a potential target for therapy." (PMID 37854071, 2023). "Salt‐inducible kinase 2 (SIK2) is a promising target for ovarian cancer therapy due to its critical role in tumorigenesis and progression." (PMID 35618488, 2022). "Collectively, our Gel Nap‐S+HG exhibited an excellent capacity of suppression on ovarian cancer proliferation and metastasis via SIK2 inhibition both in vitro and in vivo." (PMID 35618488, 2022). "The combination of PARP inhibitors and SIK2 inhibitors provides a therapeutic strategy to enhance PARP inhibitor sensitivity for ovarian cancer and TNBC." (PMID 35642638, 2022). "In recent years, other studies have found that SIK2 is located in the centrosome and plays a key role in mitosis initiation, which can affect the sensitivity of ovarian cancer to paclitaxel." (PMID 35586047, 2022). "Taken together, SIK2 positively regulates ovarian cancer motility, migration and metastasis, suggesting that SIK2 is a potential candidate for ovarian cancer treatment." (PMID 35278271, 2022). "Salt-inducible kinase 2 (SIK2) overexpression in ovarian cancer cells activates the PI3K/AKT/HIF-1α pathway, upregulates HIF-1α expression, directly upregulates the transcription of major glycolytic genes and promotes glycolysis." (PMID 36311734, 2022). "In a separate study, SIK2 was shown to enhance fatty acid and cholesterol synthesis in ovarian cancer via the SREBP1c/FASN and SREBP2/HMGCR axes, respectively." (PMID 35565396, 2022). "SIK2 also has the ability to enhance fatty acid synthesis and promote proliferation of cells in ovarian cancer cells through the PI3K pathway." (PMID 36230617, 2022). "LncRNA UCA1 has been reported to enhance paclitaxel resistance via targeting the miR-654-5p and SIK2 in ovarian cancer." (PMID 36105363, 2022). "Salt-inducible kinase 2 (SIK2) is an AMPK-related protein kinase that is required for ovarian cancer cell proliferation and metastasis." (PMID 35642638, 2022). "Another molecular mechanism by which adipocytes alter ovarian cancer cell metabolism is by the activation of Salt-inducible kinase 2 (SIK2)." (PMID 35565396, 2022). "The expression of SIK2 is upregulated in adipocyte-rich metastatic deposits in ovarian cancer and is strongly correlated with abdominal metastasis." (PMID 35216285, 2022). "Previous reports indicated that adipocytes regulating cancer metabolism activate SIK2 in ovarian cancer." (PMID 35278271, 2022).
ovarian carcinoma (continued). "SIK2 has been reported to be involved in multiple biological roles including malignant progression of ovarian cancer 44, neuronal survival after ischemia 45, and the restriction of intracellular Salmonella proliferation." (PMID 36263177, 2022). "Currently available SIK2 inhibitors have shown remarkable therapeutic effects on ovarian cancers in preclinical studies." (PMID 35618488, 2022). "It should be noted that SIK2, which is increased in obesity and related to ovarian cancer, also plays roles in hormonal signal transduction in adipose tissue." (PMID 34751020, 2022). "The released HG‐9‐91‐01 will in turn down‐regulate SIK2 activity and consequently inhibit its downstream proteins to efficiently promote apoptosis of ovarian cancer cells." (PMID 35618488, 2022). "More importantly, SIK2 expression was also positively correlated with MYLK‐pS343 expression in ovarian cancer tissues (r = 0.71, P < 0.0001), suggesting that tumours with high SIK2 expression were likely to have high MYLK‐pS343 expression." (PMID 35278271, 2022). "We have found for the first time that SIK2 regulates ovarian cancer cell motility and metastasis by directly phosphorylating MYLK at Ser343 and activating MYL2, the downstream effector of MYLK." (PMID 35278271, 2022). "RNA-Seq was performed on SKOv3 ovarian cancer cells treated with vehicle, SIK2 inhibitor, PARP inhibitors, or the combination." (PMID 35642638, 2022). "Our study showed that SIK2 is highly expressed in ovarian cancer and increases cell motility and metastasis by activating the MYLK/MYL2 pathway." (PMID 35278271, 2022). "IHC staining echoed that SIK2 expression in ovarian cancer cells was suppressed at the largest extent in Gel Nap‐S+HG group." (PMID 35618488, 2022). "The co‐expression of SIK2 and MYLK‐pS343 was associated with reduced median overall survival in human ovarian cancer samples." (PMID 35278271, 2022). "Here, we identify that SIK2 promotes ovarian cancer cell motility, migration and metastasis in vitro and in vivo." (PMID 35278271, 2022). "Various studies have confirmed that SIK2 participates in cell growth and metabolism, which is closely related to the chemotherapy of ovarian cancer." (PMID 35586047, 2022). "SIK2 is overexpressed in several cancers, including ovarian cancer, where it promotes the proliferation of metastases." (PMID 34359562, 2021). "We also showed using 3D-spheroid models of ovarian cancer cells and patient derived material that MRIA9-induced inhibition of SIK2 enhanced the sensitivity of ovarian cancer to paclitaxel therapy." (PMID 34359562, 2021). "Circ_CELSR1 overexpression also promoted the chemoresistance of ovarian cancer cells to paclitaxel via mediating the salt inducible kinase 2 (SIK2) level by targeting miR-149-5p." (PMID 34537072, 2021). "We studied the effects of the SIK2 long-term inhibition on the ability of ovarian cancer cells to survive and form colonies after paclitaxel treatment." (PMID 34359562, 2021). "Our experiment showed that MRIA9-dependent inhibition of SIK2 enhanced the paclitaxel sensitivity in all experimental models of ovarian cancer." (PMID 34359562, 2021). "The activation of SIK2 by the omental adipocytes promotes the proliferation and the growth of ovarian cancer metastases." (PMID 34359562, 2021). "Here, we report the consequences of SIK2 inhibition on mitosis and synergies with paclitaxel in ovarian cancer using a novel and selective inhibitor, MRIA9." (PMID 34359562, 2021). "More importantly, the data demonstrated the excellent potency of MRIA9 in targeting SIK2 and using patient derived primary cells, making it a promising candidate for more translational studies into ovarian cancer." (PMID 34359562, 2021). "Our study suggests selective targeting of SIK2 in ovarian cancer as a therapeutic strategy for overcoming paclitaxel resistance." (PMID 34359562, 2021).
ovarian carcinoma (continued). "Particularly in ovarian cancer, the overexpression of SIK2 in the adipocyte-rich omentum drives metastasis by promoting fatty acid oxidation and activating the PI3K pathway through direct phosphorylation." (PMID 34359562, 2021). "SIK2 is associated with poor outcomes in ovarian cancer, and previous studies have demonstrated that SIK2 induces ovarian cancer progression by activating the PI3K/AKT pathway." (PMID 35004308, 2021). "SIK2 protein is involved in the separation of centrosomes during mitosis, which can lead to ovarian cancer drug resistance." (PMID 34512721, 2021). "We observed that the specific MRIA9-induced inhibition of SIK2 reduced its enzymatic activity in ovarian cancer cells monitored by measuring the autophosphorylation on Ser385." (PMID 34359562, 2021). "Altogether, the results showed that inhibition of the kinase activity of SIK2 reduced mitotic indices in two synchronized ovarian cancer cell lines." (PMID 34359562, 2021). "It has shown that SIK2 is required for the proliferation of both prostate cancer and ovarian cancer cells." (PMID 31932581, 2020). "In accordance, our results showed that SREBP1c and SREBP2 expressions and activities were elevated by SIK2 in ovarian cancers." (PMID 31932581, 2020). "A recent study has reported that SIK2 is required for adipocyte-induced ovarian cancer (OC) survival through facilitating fatty acid oxidation." (PMID 31932581, 2020). "The misregulation of Sik2 and Sik3 being detected in several cancer cases at both genetic and epigenetic levels, and Sik3 being established as an ovary cancer marker are consistent with our finding that Siks can promote tumorigenesis." (PMID 32542037, 2020). "A SIK2 inhibitor (ARN-3236) synergizes with paclitaxel to improve outcome in preclinical ovarian cancer models." (PMID 31428057, 2019). "Using a co-culture system, we demonstrated that adipocytes isolated from omental tissue induce the calcium-dependent activation and autophosphorylation of SIK2 in ovarian cancer cells and stimulate cancer cell proliferation via the PI3K/AKT pathway." (PMID 30568223, 2019). "SIK-1, -2, and -3 have been demonstrated to be acting as tumor suppressors and also tumor promoters; the latest example being of SIK2 which was shown to be acting as a metastasis promoter in ovarian cancer." (PMID 31798532, 2019). "On the other hand, SIK2 activity at the centrosome is required for mitotic spindle assembly and survival of ovarian cancer cells." (PMID 31428057, 2019). "Following adipocyte-induced stimulation, the activated SIK2 alters metabolic effects in ovarian cancer cells by inhibiting acetyl-CoA carboxylase and promoting fatty acid oxidation." (PMID 30723708, 2019). "More recently, we found that SIK2 plays an important role in the regulation of ovarian cancer cell metabolism in the context of cancer metastasis to the adipocyte-rich metastatic niche." (PMID 30568223, 2019). "The data identified SIK2 as a key molecule at the hub of the adipocyte-induced signaling cascades and provided a strong rationale for targeting SIK2 in ovarian cancer therapy." (PMID 28929459, 2018). "SIK2 is highly expressed in the adipocyte-rich metastatic deposits of ovarian cancer." (PMID 40384110, 2025). "SIK2 overexpression promoted ovarian cancer cells intraperitoneal metastasis." (PMID 39256355, 2024). "The study suggests that future development of inhibitors that selectively target SIK2 could contribute to prevent paclitaxel resistance in ovarian cancer patients, improving their prognosis." (PMID 39256355, 2024). "SIK‐2 can participate in fatty acid oxidation and mitochondrial respiration, which might sustain adipocyte‐induced metastasis of ovarian cancer." (PMID 37605299, 2023). "Thus, SIK2 impairs glucose metabolism and increases mitochondrial fission in ovarian cancer cells by activating the PI3K/AKT/HIF-1a pathway." (PMID 37508561, 2023).